HIF3A (hypoxia inducible factor 3 subunit alpha)
Description:
Acts as a transcriptional regulator in adaptive response to low oxygen tension. Acts as a regulator of hypoxia-inducible gene expression. Functions as an inhibitor of angiogenesis in hypoxic cells of the cornea. Plays a role in the development of the cardiorespiratory system. May also be involved in apoptosis (By similarity). [Isoform 2]: Attenuates the ability of transcription factor HIF1A to bind to hypoxia-responsive elements (HRE) located within the enhancer/promoter of hypoxia-inducible target genes and hence inhibits HRE-driven transcriptional activation. Also inhibits hypoxia-inducible ARNT-mediated gene expression. [Isoform 3]: Attenuates the ability of transcription factor HIF1A to bind to hypoxia-responsive elements (HRE) located within the enhancer/promoter of hypoxia-inducible target genes and hence inhibits HRE-driven transcriptional activation. [Isoform 4]: Attenuates the ability of transcription factor HIF1A and EPAS1/HIF2A to bind to hypoxia-responsive elements (HRE) located within the enhancer/promoter of hypoxia-inducible target genes and hence inhibits HRE-driven transcriptional activation. May act as a tumor suppressor and inhibits malignant cell transformation. [Isoform 5]: Attenuates the ability of transcription factor HIF1A to bind to hypoxia-responsive elements (HRE) located within the enhancer/promoter of hypoxia-inducible target genes and hence inhibits HRE-driven transcriptional activation.
Synonyms: bHLHe17; IPAS; MOP7; PASD7; HIF-3A; HIF3-alpha-1
Tractability: Small molecule: a structure with a bound ligand is known. Antibody: its Gene Ontology location is reachable by antibodies, with high confidence. PROTAC: UniProt records ubiquitination sites on it; ubiquitination databases record sites on it.
Gene: Protein-coding gene on chromosome 19 (46,297,042 to 46,343,433, forward strand). Ensembl gene ENSG00000124440.
Subcellular location: Nucleus; Cytoplasm; Nucleus speckle; Mitochondrion
Subcellular location (Human Protein Atlas): Cytosol; Nucleoplasm; Plasma membrane
Pathways (Reactome):
Cellular responses to stimuli: Oxygen-dependent proline hydroxylation of Hypoxia-inducible Factor Alpha; Regulation of gene expression by Hypoxia-inducible Factor
Developmental Biology: Transcriptional regulation of pluripotent stem cells
Metabolism of proteins: Neddylation
Gene Ontology:
Molecular function: DNA-binding transcription factor activity, RNA polymerase II-specific; RNA polymerase II cis-regulatory region sequence-specific DNA binding; RNA polymerase II transcription regulatory region sequence-specific DNA binding; DNA binding; DNA-binding transcription factor activity; protein dimerization activity
Biological process: intracellular oxygen homeostasis; regulation of transcription by RNA polymerase II; regulation of DNA-templated transcription
Cellular component: chromatin; cytoplasm; cytosol; nucleoplasm; nucleus; mitochondrion; nuclear speck; transcription regulator complex
Genetic constraint (gnomAD): Loss-of-function variants: 34 observed, 54.33 expected, observed/expected ratio (o/e) 0.63, 90% interval 0.47 to 0.83. The upper end of that interval is the gene's LOEUF score, 0.83, which puts it in group 3 of 6, group 1 being the genes least tolerant of losing a copy. Missense variants: 813 observed, 859.92 expected, observed/expected ratio (o/e) 0.95, 90% interval 0.89 to 1. Synonymous variants: 349 observed, 359.37 expected, observed/expected ratio (o/e) 0.97, 90% interval 0.89 to 1.06.
Homologues: Orthologues: chimpanzee HIF3A (99% identical), macaque HIF3A (96% identical), dog HIF3A (89% identical), pig HIF3A (86% identical), guinea pig HIF3A (85% identical), mouse Hif3a (82% identical), rat Hif3a (81% identical), zebrafish hif1al (38% identical), Drosophila melanogaster sima (32% identical), Drosophila melanogaster trh (23% identical), Caenorhabditis elegans hif-1 (22% identical). Paralogues in human: HIF1A (39% identical), EPAS1 (38% identical), NPAS3 (25% identical), SIM2 (24% identical), SIM1 (22% identical), NPAS1 (22% identical), NPAS4 (18% identical).
Diseases named in the same sentence as HIF3A in open-access papers:
HIF3A is named in the same sentence as 90 diseases in open-access papers, as found by Europe PMC text mining. Sharing a sentence is not in itself a finding about the gene and the disease. The quoted sentences say what the papers report.
Obesity (29 papers, 2015 to 2026). Accumulation of substantial excess body fat. "Previous studies have reported that increased HIF3α promoter methylation is associated with obesity and higher plasma glucose levels and waist-hip ratio and adipose tissue dysfunction, T2DM and lower insulin sensitivity." (PMID 36992770, 2022). "Several studies showed that HIF3A is methylated and this modification is significantly associated to obesity." (PMID 35096807, 2021). "The results across each method indicated that a higher BMI causally influenced higher HIF3A methylation, suggesting that alterations in DNA methylation are a downstream effect of obesity." (PMID 30842548, 2019). "An epigenome-wide association study (EWAS) of obesity showed that differential methylation in intron 1 of the hypoxia-inducible factor 3a (HIF3A) gene in blood were associated with increased body mass index (BMI)." (PMID 28978046, 2017). "Using a multivariate linear regression model, we then tested the interaction term (SNP × obesity group), and found a significant interaction between G-allele number in the HIF3A rs3826795 polymorphism and obesity on the plasma ALT (P = 0.042)." (PMID 28754107, 2017). "Hypoxia Inducible Factor 3 Alpha Subunit (HIF3A) DNA has been demonstrated to be associated with obesity in the methylation level, and it also has a Body Mass Index (BMI)-independent association with plasma alanine aminotransferase (ALT)." (PMID 28754107, 2017). "In conclusion, our data suggest that HIF3A expression and methylation in adipose tissue is related to its dysfunction, making HIF3A an important factor involved in the complex etiology of obesity and associated comorbidities." (PMID 27346320, 2016). "Rs8102595 showed a nominal significant association with AT HIF3A methylation levels as well as with obesity and fat distribution." (PMID 27346320, 2016). "We show that higher HIF3A mRNA expression in both subcutaneous and visceral adipose tissue is associated with higher BMI and obesity related traits." (PMID 27346320, 2016). "We used partial correlation analyses adjusted for age and gender, to examine the associations between HIF3A methylation levels and obesity-related anthropometric/metabolic phenotypes." (PMID 26717317, 2015). "HIF-3αhas not been investigated as thoroughly as the other α subunits, but it is usually regarded as a negative regulator of HIF-1αand HIF-2α.The causal relation between obesity and HIF3A methylation is far from definitive conclusions." (PMID 26717317, 2015). "Furthermore, higher DNAm in HIF3A is associated with obesity in children and BMI in adult blood and adipose tissue, which suggest a role in metabolic processes." (PMID 41246799, 2026). "HIF3A has been reported to promote high-altitude adaptation in both Tibetan pigs and yaks, although some studies suggest it is also associated with obesity." (PMID 39497743, 2024). "It is thought that upregulation of HIF3A may be the result of the hypoxia associated with sleep apnea or other disordered breathing secondary to high BMI and, therefore, obesity." (PMID 37899888, 2023). "Aberrant methylation of NPY, ADRB3, IGF1, and HIF3a have all been linked to obesity." (PMID 37899888, 2023). "A novel use of HIF3A may be as a biomarker for the likelihood of developing obesity or as a biomarker for diagnostic confirmation of obesity-induced sleep apnea." (PMID 37899888, 2023). "In the event that increased methylation of HIF3A is found to be a cause of increased adiposity, then HIF3A may be considered a potential therapeutic target against the development of obesity." (PMID 37899888, 2023). "Beyond the association with concurrent adiposity (birth weight or obesity), HIF3A methylation at birth potentially might have an additional value." (PMID 31138846, 2019). "The epigenetic signature of the HIF3A gene may be a cause or a result of the prolonged high blood glucose levels seen in cases of obesity." (PMID 28978046, 2017).
Obesity (continued). "In conclusion, we found that obesity interacts with the HIF3A rs3826795 polymorphism on plasma ALT, and the effect of rs3826795 on ALT in obese children could be mediated by HIF3A DNA methylation." (PMID 28754107, 2017). "We therefore assessed whether the HIF3A methylation is associated with obesity and other obesity-related phenotypes in Chinese children." (PMID 26717317, 2015). "In summary, this study has validated the association between HIF3A methylation and obesity in Chinese children for the first time, reported a new CpG site at HIF3A associated with obesity, and explored a BMI-independent association between HIF3A methylation and plasma ALT level." (PMID 26717317, 2015). "First, that an epigenetic mark associated with BMI and potentially obesity (DNA methylation of cg22891070 in HIF3A) may be modifiable, in this case by gastric bypass and or weight loss, and thus, if appropriate, may be tractable to treatment." (PMID 25651499, 2015). "The study aimed to assess whether there were nearby CpG sites with a stronger effect associated with obesity, and whether there were other obesity-related phenotypes associated with HIF3A methylation." (PMID 26717317, 2015). "A genome-wide analysis shows a connection between the methylation of the HIF3A locus in adipose tissue and adult obesity." (PMID 38717999, 2024). "They found higher methylation levels in children with obesity at two sites, 46801699 and 46801642, in the HIF-3α gene." (PMID 36864020, 2023). "HIF3A is a novel player that controls the energy metabolism with potential applications in developing therapy to fight metabolic disorders, as obesity, T2D and ultimately cancer." (PMID 35096807, 2021). "For example, a strong correlation has been reported between the hypoxia-inducible factor 3-alpha gene (HIF3A) and BMI, and methylation of this gene is associated with obesity and adipose tissue dysfunction." (PMID 32392798, 2020). "For example, two CpG methylation sites in intron 1 of HIF3A gene, cg16672562, and cg46801562, have significant correlation with obesity." (PMID 30743315, 2019). "Previous studies have shed light on the association between Hypoxia Inducible Factor 3 Alpha Subunit (HIF3A) DNA methylation and obesity-related traits." (PMID 28754107, 2017). "This is the first study to report the interaction between obesity and HIF3A gene in relation with ALT, and also to reveal a mediation effect among the HIF3A polymorphism, methylation and ALT." (PMID 28754107, 2017). "We primarily focused on DMPs of the HIF3A gene that were previously reported in an Infinium study to be involved in adult obesity." (PMID 28978046, 2017). "The results provided new evidence to the function of the HIF3A gene and the mechanism linking obesity and ALT." (PMID 28754107, 2017). "HIF3A methylation and its expression in adipose tissues is fat deposit-specific and are related to obesity and adipose tissue dysfunction." (PMID 28978046, 2017). "Our data support previous reports on the epigenetic association of differential methylation in HIF3A in adults that illustrate the importance of differential DNA methylation of the HIF3A gene in obesity through changes in BMI." (PMID 28978046, 2017). "In paired samples of subcutaneous AT (SAT) and visceral AT (VAT) from 603 individuals, we measured HIF3A mRNA expression and analyzed its correlation with obesity and related traits." (PMID 27346320, 2016). "HIF3A expression and methylation in AT are fat depot specific, related to obesity and AT dysfunction." (PMID 27346320, 2016). "Human studies have revealed that a rise in adipose tissue accumulation in obesity is linked to enhanced methylation at the hypoxia-inducible factor 3A (HIF3A) locus in blood cells and adipose tissue, but not in the skin." (PMID 33639960, 2021). "HIF3A could possibly represent a mechanistic link between obesity and metabolic complications since SAT gene expression is inversely correlated with systemic insulin resistance." (PMID 32180562, 2020).
Obesity (continued). "It is important to emphasize that previous reports, in addition to the current study, only tested for associations between HIF3A methylation and BMI levels, which do not indicate the causality of HIF3A methylation alterations to obesity." (PMID 31246962, 2019). "Furthermore, we identified that DNA methylation levels of the obesity-related gene HIF3A showed a positive correlation with father’s BMI in the cord blood of male children (p-value = 0.041)." (PMID 31246962, 2019). "In this regard, we selected four maternally imprinted genes (MEST/PEG1, SNRPN/PEG4, NNAT/PEG5, and SGCE/PEG10), three paternally imprinted loci (H19-IG DMR, IGF2 DMR0, and MEG3-IG DMR) and one obesity related gene HIF3A to check the correlation of male BMI with sperm DNA methylation." (PMID 31246962, 2019). "This study aims to identify the association between HIF3A polymorphism and plasma ALT, and further to determine whether the effect of HIF3A polymorphism on ALT could be modified by obesity or mediated by DNA methylation." (PMID 28754107, 2017). "Hence, the heritability and thereby potential genetic influence on HIF3A DNA methylation in the blood is at the same magnitude as that seen for obesity and T2D." (PMID 27594926, 2016). "HIF3A might function as an accelerator of adipogenesis in situations of excess of energetic supply and might contribute to the etiology of secondary obesity-induced pathologies by allowing a stronger induction of HIF1α-mediated proinflammatory signaling." (PMID 27346320, 2016). "We therefore tested the hypothesis that expression of HIF3A in human subcutaneous and visceral adipose tissue is related to obesity, parameters of fat distribution and adipose tissue function." (PMID 27346320, 2016). "A detailed explanation of the mechanisms by which HIF-3α is involved in the regulation of metabolic processes may be important for the development of effective strategies for the pharmacological prevention or treatment of obesity." (PMID 39456823, 2024). "However, the relation among obesity, plasma ALT, HIF3A polymorphism and methylation remains unclear." (PMID 28754107, 2017). "In the current study, by testing the nearby SNP and conducting interaction analysis and mediation analysis, we identified that the HIF3A rs3826795 polymorphism interacts with obesity on ALT, and HIF3A DNA methylation could act as a mediator in the effect of rs3826795 on ALT in obese children." (PMID 28754107, 2017). "There is a positive significant association between HIF3A methylation and BMI, but it is not clear whether differential methylation of HIF3A is a cause or consequence of obesity." (PMID 28978046, 2017). "Moreover, greater methylation of HIF3A at the same position in blood DNA was also observed in obese children, whereas modulation of HIF3A methylation status by nutrients suggested that methylation is the consequence, but not cause of obesity." (PMID 33088334, 2020). "Further studies were needed for understanding the mechanism of the relation among obesity, ALT and the HIF3A gene, and also the mechanism of HIF3A meQTL." (PMID 28754107, 2017). "First of all, though we have tested the relation among obesity, ALT, HIF3A SNP and methylation by conducting the interaction analysis and the mediation analysis, the case-control design of the current study means that we cannot assess the causality." (PMID 28754107, 2017). "HIF3A expression was significantly higher in SAT compared to VAT and correlated with obesity and parameters of AT dysfunction (including CRP and leucocytes count)." (PMID 27346320, 2016). "HIF3A DNA methylation was tested in 110 children with severe obesity and 110 non-obese age- and gender- matched controls." (PMID 28754107, 2017). "However, the relation among obesity, plasma ALT, HIF3A SNPs and methylation remains unclear." (PMID 28754107, 2017).
Insulin resistance (11 papers, 2016 to 2024). Increased resistance towards insulin, that is, diminished effectiveness of insulin in reducing blood glucose levels. "Methylation of hypoxia-inducible factor-3α (HIF3A) was previously demonstrated to be highly associated with insulin resistance (IR) in patients with gestational diabetes mellitus (GDM)." (PMID 31652442, 2019). "Furthermore, HIF3A expression in subcutaneous adipose tissue was adversely associated with insulin resistance." (PMID 30743315, 2019). "In women with gestational diabetes, berberine is known to reduce insulin resistance by inhibiting hypoxia-inducible factor-3α (HIF3A) methylation." (PMID 36770960, 2023). "Studies have shown a significant correlation between HIF3A methylation and insulin resistance in gestational diabetes mellitus." (PMID 36770960, 2023). "Recently, studies have shown that HIF3A expression and methylation are related to adipose tissue dysfunction, insulin resistance, and gestational diabetes mellitus." (PMID 34975464, 2021). "Studies demonstrated that the expression and methylation of HIF3A in adipocyte were fat depot-specific and is related to metabolism in adipose tissue and insulin resistance, which are believed as two factors contributing to GDM progression." (PMID 31652442, 2019). "The possible physiological importance of HIF3A in SAT was highlighted by our novel findings of significant negative associations between HIF3A expression in SAT and both BMI and whole-body insulin resistance." (PMID 27594926, 2016). "In this study, we investigated associations between BMI and HIF3A DNA methylation in the blood and SAT from the same individuals, and whether HIF3A gene expression in SAT and skeletal muscle biopsies showed associations with BMI and insulin resistance." (PMID 27594926, 2016). "Interestingly, HIF3A expression in SAT, but not in muscle, associated negatively with BMI and whole-body insulin resistance." (PMID 27594926, 2016).
gestational diabetes (9 papers, 2019 to 2025). Carbohydrate intolerance first diagnosed during pregnancy. "This is supported by other studies showing reduced expression of HIF3A in women with gestational diabetes." (PMID 39456823, 2024). "It has been reported that HIF3A methylation in women with gestational diabetes is higher than in normal pregnant women." (PMID 36770960, 2023). "Emerging evidence also suggests an influence of gestational diabetes and maternal pre-pregnancy BMI on cord blood methylation at a second HIF3A promoter region." (PMID 31262346, 2019). "This idea is supported by several studies showing that gestational diabetes or pre pregnancy BMI indeed influenced cord blood HIF3A methylation." (PMID 31138846, 2019). "In addition, a correlation has been observed between HIF3A promoter methylation and gestational diabetes." (PMID 39456823, 2024).